BRCA1 (BRCA1 DNA repair associated)
Diseases named in the same sentence as BRCA1 in open-access papers (continued):
Sharing a sentence is not in itself a finding about the gene and the disease.
breast cancer (continued). "This is in consistence with results from other studies on breast cancer in patients of African ancestry where plausible causal variants in BRCA2 gene were predominant compared to BRCA1." (PMID 32959997, 2020). "In breast cancer patients who are BRCA1 mutation carriers, CCND1 expression was significantly reduced." (PMID 32685473, 2020). "The unadjusted odds (in binary logistic regression analysis) of a breast cancer being MF/MC in BRCA2 mutation carriers was 5.8 times greater than in a BRCA1 mutation carrier who developed breast cancer (CI: 3.31–10.12) (p < 0.001)." (PMID 32022473, 2020). "Low expression of BRCA1 is correlated with breast cancer transformation and the risk of developing leukemia was increased in patients who received treatment for BRCA1 mutation-associated breast cancer." (PMID 32826945, 2020). "We included 163 patients with synchronous bilateral breast cancer who had germline BRCA1/2 mutations testing." (PMID 32117708, 2020). "In mammary tumors from patients mutated for BRCA1, expression of these proteins is also impacted as a consequence of BRCA1 loss of function." (PMID 32290274, 2020). "Breast cancer was also assessed and the cumulative risk at the age of 80 years was estimated to be 72% (95% CI, 65–79%) for BRCA1 carriers and 69% (95% CI, 61–77%) for BRCA2." (PMID 33086730, 2020). "Breast cancer risk management for BRCA1/2 mutation carriers encompass the possibility of intensive breast surveillance aimed at early detection, or bilateral prophylactic mastectomy (BPM)." (PMID 31832891, 2020). "In the present study, our data clearly demonstrate that expression of ICN1, representing Notch1 activation, promotes Brca1-associated mammary tumour formation." (PMID 32591500, 2020). "In conclusion, we report a higher than anticipated prevalence of multifocality/multicentricity amongst female BRCA1/2 mutation carriers diagnosed with breast cancer." (PMID 32022473, 2020). "Our research provides comprehensive and new insights for the identification of biomarkers connected with BRCA mutations, availing diagnosis and treatment of breast cancer and BRCA1/2-mutant breast cancer patients." (PMID 31998560, 2020). "For individuals with a BRCA1/2 mutation, the risk of developing breast cancer is 69 and 62%, respectively." (PMID 33015058, 2020). "In our study, TNBCs account for 25% of all BRCA-variant breast cancers present in probands: 70% of these was related to BRCA1 PVs and 30% was associated to BRCA2 PVs." (PMID 32380732, 2020). "Published studies to date suggest that the breast cancer risk in PHTS is similar to that in women with germline PVs in BRCA1/BRCA2." (PMID 32533092, 2020). "The inheritance of mutated BRCA1 or BRCA2 alleles results in a lifetime risk of breast cancer as high as 80%." (PMID 33257598, 2020). "Identification of BRCA1 mutations greatly improves the preventive strategies and management of breast cancer." (PMID 31908633, 2020). "The study included 222 BRCA1 mutation carriers, 168 of which with a history of breast cancer, and 359 BRCA2 mutation carriers, 109 with a history of breast cancer, respectively." (PMID 32140806, 2020). "Lastly, 8 showed synergismwith 1 in BRCA1/2 deficient breast cancer cells, suggestinga synthetically lethal interaction; these results were mirrored in vivo in breast cancer models." (PMID 33135887, 2020). "Our study accord with a pathogenic BRCA1 mutation: p.Ile1845fs and identified 94 carriers (0.40%) in 23,481 breast cancer patients, and 11 (0.17%, 11/6489) in controls." (PMID 31908633, 2020). "In the BRCA1 mutation group, there were 268 breast cancers and 20 breast cancer-related deaths among the 990 women in the surveillance cohort (2.0%) and eight breast cancers and one death among the 722 women in the mastectomy cohort (0.1%)." (PMID 33238387, 2020).
breast cancer (continued). "In particular, we investigated the effects of biallelic inactivation of BRCA1/2 genes on the somatic mutations, and copy number (CN) abnormalities (CNAs) and clinical features of the resulting breast cancers." (PMID 33067557, 2020). "About 70% of breast cancers in BRCA1 mutation carriers and up to 23% of BRCA2 carriers are triple-negative." (PMID 33282730, 2020). "Nkondjock and colleagues observed that women with BRCA1/2 pathogenic germline gene variants who experienced their maximum BMI at > 43-years were at a nearly 3-fold increased risk of breast cancer (OR 2.90, 95%CI 1.01,8.36)." (PMID 32165993, 2020). "Recently we and other groups have provided direct genetic and pharmacological proof that the RANKL/RANK pathway plays an essential role in the progression of familial BRCA1-mutated associated breast cancer." (PMID 32850393, 2020). "By age 70, the median cumulative risk for BRCA1 mutation carriers is about 50% to 80% for breast cancer and 24% to 40% for ovarian cancer." (PMID 32882684, 2020). "Regarding PA, activity in adolescence and lifetime activity appear to have some association with breast cancer risk-reduction among women with BRCA1/2 pathogenic germline gene variants collectively." (PMID 32165993, 2020). "MF/MC breast cancer was identified in 26.9% of BRCA1/2 mutation carriers who developed breast cancer." (PMID 32022473, 2020). "Loss of BRD7 or BRCA1 in breast cancer cells prevents expression of ERα, and makes the cells resistant to fulvestrant, an antiestrogen drug that is often used to treat breast cancer." (PMID 32992509, 2020). "CCNE1, NPBWR1, A2ML1, EXO1 and TTK displayed good prognostic/diagnostic value for breast cancer and BRCA1/2-mutant breast cancer." (PMID 31998560, 2020). "Genetic factors in the form of BRCA1 mutations are significant contributors to the high prevalence of breast cancer among Pakistani population." (PMID 32063924, 2020). "Adjustment for oestrogen receptor status gave odds of a BRCA2 mutation carrier developing MF/MC breast cancer 4.2 times greater than a BRCA1 mutation carrier (CI: 2.12–8.19) (p < 0.001)." (PMID 32022473, 2020). "Above age 70 to 75 years, the cumulative risk of breast cancer and ovarian cancer among BRCA1 and BRCA2 mutation carriers stabilizes." (PMID 32882684, 2020). "Afrequency of 2.9-24% of BRCA1/2 mutations has been reported infamilial breast cancer patients of South India." (PMID 32453341, 2020). "Regular use of aspirin and other non-steroidal anti-inflammatory drugs (NSAIDs) has been consistently associated with reduced risk of cancers, including breast cancer, and reduced breast cancer risk in high-risk women with BRCA1 and BRCA2 mutations." (PMID 32731638, 2020). "We found that this mutation protected against the development of breast cancer in BRCA1/2 mutation carriers." (PMID 32175645, 2020). "BRCA1 mutations occur in hereditary breast cancer and OC, but sporadic BRCA1 promoter methylation is observed in 15–30% of OC." (PMID 32183385, 2020). "Because of the fact that among our patients with BRCA1/2 mutations only one had BRCA2 mutation, the results and discussion concern about patients with breast cancer and BRCA1 mutation." (PMID 32322271, 2020). "Pathogenic variants (PVs) carriers in BRCA1 or BRCA2 are associated with an elevated lifetime risk of developing breast cancer (BC) and/or ovarian cancer (OC)." (PMID 32438681, 2020). "We found that the mutation frequency of ERCC6 (1.8%) in breast tumors was similar to those of known breast cancer susceptibility genes, such as BRCA1 (2.9%), BRCA2 (2.9%), BLM (1.9%), FGFR2 (1.5%), and CHEK2 (1.0%)." (PMID 33277540, 2020). "A large number of previous studies have reported BRCA1/2 as the most important tumor suppressor gene associated with breast cancer and ovarian cancer." (PMID 32117708, 2020).
breast cancer (continued). "In conclusion, we found that SIRT4 regulation of BITCs negatively modulated mammary tumorigenesis through suppression of SIRT1 via glutamine metabolism and that SIRT4 deficiency decreased H4K16ac and BRCA1 expression in breast cancer." (PMID 32863939, 2020). "In this study, we seek to determine the mechanism by which BRCA1 is involved in mitophagy and its impact on therapeutic treatment of BRCA1‐associated breast cancer." (PMID 32195105, 2020). "Current research confirms that breast cancer susceptibility gene 1/2 (BRCA1/2) is the most important susceptibility gene associated with HOCS." (PMID 32356124, 2020). "Female carriers of a monoallelic BRCA1/2 PV/LPV have a 40–66% lifetime risk of developing breast cancer and a 13–46% lifetime risk of ovarian cancer." (PMID 33110458, 2020). "We genotyped 2464 women with breast cancer diagnosed below age 41 years for twenty recurrent germline mutations in six genes, including BRCA1, BRCA2 CHEK2, PALB2, NBN, and RECQL." (PMID 32824581, 2020). "On the other hand, it was argued that the excess lymphocyte infiltration in breast cancers involving BRCA1 mutations is simply an exaggeration of a phenotypic feature that has no bearing on disease progression." (PMID 32971948, 2020). "The MR result of BRCA1 carriers from CIMBA suggested that RA is associated with a reduced risk of breast cancer, although most of the participants were Caucasian." (PMID 33167385, 2020). "Summary of main studies investigating the role of breast conserving surgery and risk reducing mastectomy in breast cancer patients with BRCA1/2 mutations." (PMID 33194613, 2020). "Several PARP inhibitors (PARPis) have been successful in various malignancies with HRR gene mutations including BRCA1/2, especially in breast cancer and ovarian cancer." (PMID 33233320, 2020). "It has been well-reported in previous studies that positive carriers for BRCA1/BRCA2 have high cumulative risk estimates for developing breast cancer reaching 72% for BRCA1 carriers and 69% for BRCA2 carrier by age of 805." (PMID 33067490, 2020). "In contrast to BRCA1-associated breast cancers, BRCA2-associated tumors are very similar to sporadically-occurring “luminal-type” tumors." (PMID 33117676, 2020). "On the other hand, approximately 80% of breast cancers that present in patients with BRCA1 germline mutations are TN tumors with basal-like profile." (PMID 32276534, 2020). "BRCA1-A mutations that disrupt BRCA1 sequestration have been identified in breast cancer patients, suggesting a tissue tropism similar to BRCA1 mutations." (PMID 33142801, 2020). "Breast cancer cells with deleterious mutations in BRCA1/2 are deficient in the repair mechanism for DNA double-strand breaks, leaving these tumors highly dependent on the repair pathway for single-strand breaks." (PMID 32455662, 2020). "In line with this, at best 1 out of 5 patients with triple negative breast cancer, the most common form of BRCA1 mutation-associated breast cancer, has been shown to benefit from single agent PD-1 blockade." (PMID 33718107, 2020). "Beyond germline pathogenic variants (gPVs) in breast cancer genes 1 and 2 (BRCA1/2), alterations in BRIP1, RAD51C, and RAD51D and mismatch repair (MMR) genes also enhance EOC risk." (PMID 32455595, 2020). "Loss of the wild-type BRCA1 allele has been shown to increase lipid production in breast cancer cells." (PMID 32992445, 2020). "c-kit is overexpressed in AA breast cancer patients and is involved in the growth and survival of BRCA1 mutated cells." (PMID 32824813, 2020). "In cases of breast cancer with BRCA1 mutations, activated RANKL/RANK signaling has been reported to increase CSC expansion." (PMID 33014829, 2020).
breast cancer (continued). "The women visiting the clinic had a family history of breast or ovarian cancer, and in some the cancer is a result of mutations in breast cancer predisposing genes (such as BRCA1/2)." (PMID 32756364, 2020). "Recently, an association between aspirin use and BRCA1 promoter methylation that affects the mortality after breast cancer has been shown." (PMID 33143725, 2020). "While BRCA1 mutations occur in the majority of hereditary breast cancers, BRCA1 gene promoter methylation is associated with sporadic breast cancers." (PMID 32183060, 2020). "A previous study has demonstrated that EZH2 can inhibit breast cancer susceptibility gene 1 (BRCA1) in breast cancer." (PMID 31830649, 2020). "Recent studies of germline BRCA1/2 mutations in patients with breast cancer have suggested that these mutations have a similar prognosis, though they exhibit different effects on the efficacy of chemotherapy." (PMID 32736562, 2020). "A high level of BRCA1 mutations in breast cancer suggests the activation of the autophagic and apoptotic machinery in response to fluorouracil, doxorubicin, and cyclophosphamide chemotherapy." (PMID 31896739, 2020). "To date, multiple breast cancer predisposition genes have been identified, mainly from studies of women of European ancestry, including BRCA1, BRCA2, PALB2, CHEK2, and ATM, which together accounted for 25% of the familial risk." (PMID 32318955, 2020). "Previously, we observed 1q12 displacement block in lymphocytes of breast cancer patients with a BRCA1 gene mutation and in 1q12 polyploid primary stem cancer cells of the breast tumor." (PMID 32714923, 2020). "There were 338 germline BRCA mutation carriers in the POSH study breast cancer cohort; focality data were missing in 37 cases, leaving 180 women with a BRCA1 mutation and 121 with a BRCA2 mutation for analysis." (PMID 32022473, 2020). "This manuscript summarizes and updates recent evidence on the effects of vitamin D in breast cancer with a special emphasis on its triple-negative variants that are frequently similar to BRCA1-deficient cases." (PMID 32456160, 2020). "Breast cancer susceptibility gene (BRCA1 and BRCA2) mutations, which confer substantial lifetime risks of breast and ovarian cancers, influence oncogenesis and metastasis of breast cancer." (PMID 31998560, 2020). "In this study we investigated the profiling of the BRCA1: p.Ile1845fs variant in Han Chinese breast cancer." (PMID 31908633, 2020). "Pathogenic BRCA1 mutation carriers have a 72% lifetime risk of developing breast cancer, while the risk for BRCA2 mutation carriers is 69%." (PMID 32070378, 2020). "Bilateral breast cancer and ovarian and prostate cancers are thought to be associated with pathogenic variants in the BRCA1 and BRCA2 genes." (PMID 31965555, 2020). "More interestingly, some candidate genes displayed potential therapeutic and diagnostic value, especially for BRCA1/2-mutant breast cancer." (PMID 31998560, 2020). "This review analyses the published data on fertility treatment and risk of ovarian and breast cancer in BRCA1/2 mutation carriers." (PMID 32719921, 2020). "BRCA1 mutation breast cancers usually express as TNBC subtype, and associate with higher tumor grade, poorer differentiated, higher proportion of medullary and atypical medullary carcinomas." (PMID 33273622, 2020). "Mutations in BRCA1 predispose carriers predominantly to cancers of the breast and ovaries (mostly BLBC and HGSOC), though the mechanism driving tumorigenesis in these patients is still unclear." (PMID 32527287, 2020).
breast cancer (continued). "The examples above show the significant difficulty which healthy women with a BRCA1/2 gene mutation face when encountering their breast cancer risk." (PMID 32513307, 2020). "Breast cancer susceptibility gene 1/2 (BRCA1/2) is the most important susceptibility gene associated with hereditary ovarian cancer (HOC)." (PMID 32356124, 2020). "In vitro evidence supports BCAAs as a factor for breast cancer development in human breast epithelial cells, demonstrating that a knock-in of a single allele BRCA1 mutation increased BCAA levels." (PMID 33024201, 2020). "Mutations in BRCA1 are responsible for approximately 40% of inherited breast cancers and more than 80% of inherited breast and ovarian cancers." (PMID 32842712, 2020). "Approximately 10-15% of breast cancer cases are caused by hereditary genetic mutation of BRCA1 and BRCA2 genes." (PMID 32856854, 2020). "We highlight several DNA-methylation-specific challenges that should be considered when incorporating information on DNA methylation marks into risk prediction models, using BRCA1, a highly penetrant breast cancer susceptibility gene, as an example." (PMID 32066913, 2020). "The majority of breast cancers are sporadic while 5–10% are familial, and approximately 40–50% of the familial breast tumours are associated with germ-line mutations in breast cancer 1 early onset (BRCA1) gene." (PMID 33212987, 2020). "The polymorphic variants of BRCA1, which lead to amino acidsubstitutions, have a known pathogenic role in breast cancer." (PMID 32453341, 2020). "Breast Cancer: Certain variants in the BRCA1 and BRCA2 genes are known to elevate Breast Cancer risk significantly." (PMID 32694572, 2020). "In 54 BRCA1-deficient breast cancers in this cohort, increased expression of NOTCH1 also correlated with TNBC and the basal-type." (PMID 32591500, 2020). "We used clinical and molecular data from 1101 TCGA breast-cancer patients to evaluate the downstream effects of BRCA1 and BRCA2 germline mutations in tumors." (PMID 32997669, 2020). "Heterozygous germline mutations in BRCA1/2 are responsible for a large fraction of hereditary breast cancers." (PMID 32974031, 2020). "Poly (ADP-ribose) polymerase (PARP) inhibitors are approved for the treatment of breast cancer susceptibility genes 1 and 2 (BRCA1/2) mutant ovarian and breast cancers, and are now being evaluated in metastatic castration-resistant prostate cancer (mCRPC)." (PMID 32171277, 2020). "The clinical utility of GWAS in determining those high-penetrance breast cancer gene mutations was initially very high back in the 1990s, when BRCA1 and BRCA2 were first cloned." (PMID 32823908, 2020). "In this study of families with the deletion BRCA1 3450del4 in Tolima and Huila we confirmed its association with familial aggregation of breast cancer." (PMID 32220173, 2020). "Currently, there appears to be little justification for complete sequencing of moderate penetrance genes, such as those of ATM, BRIP1, CHEK2, PALB2, and RAD50 in BRCA1/BRCA2-negative high-risk breast cancer families." (PMID 32823908, 2020). "BRCA1 (Breast cancer antigen 1) or BRCA2 (Breast cancer antigen 2) mutations confer the women with a 50–80% lifetime risk of breast cancer and 16–65% lifetime risk of ovarian cancer." (PMID 33379383, 2020). "In the case of breast cancer, the surveillance follow-up should copy that in BRCA1/BRCA2 mutation carriers." (PMID 33322746, 2020). "In 1994, the Breast Cancer Linkage Consortium (BCLC) highlighted a statistically significant increased risk of CRC in a population of BRCA1 mutation carriers (RR = 4.11, 95% CI 2.36–7.15)." (PMID 33198203, 2020). "The present study assessed the proportion of recently diagnosed, high risk, breast cancer patients treated in a US community oncology setting, who were tested for BRCA1/BRCA2 variants in accordance with NCCN guidelines." (PMID 32518611, 2020).